CXCL9 (C-X-C motif chemokine ligand 9)
Diseases named in the same sentence as CXCL9 in open-access papers (continued):
Sharing a sentence is not in itself a finding about the gene and the disease.
nasopharyngeal carcinoma (9 papers, 2013 to 2023). A carcinoma arising from the nasopharyngeal epithelium. "Hsin and colleagues have indicated that serum CXCL9 is highly increased in patients with nasopharyngeal carcinoma which is associated with poor prognosis and survival rate." (PMID 34680466, 2021). "The results of this study suggest that the gene expression of CXCL9/10/11 have up-regulated is related to avoiding immune destruction that can use as an early detection biomarker of nasopharyngeal cancer in Indonesian patients." (PMID 32986357, 2020). "For example, pre-treatment serum CXCL-9 levels in patients with nasopharyngeal carcinoma (NPC) were found not only to be significantly higher in those with higher stage disease but predicted for poorer prognosis in terms of overall survival and disease-free survival." (PMID 29157300, 2017). "We previously demonstrated that circulating plasma CXCL9 levels were differentially elevated in the both groups of patients with oral cavity squamous cell carcinoma and nasopharyngeal carcinoma by the multiplex suspension array system, a high-throughput proteomic platform." (PMID 24278236, 2013). "The aim of this cohort study was to examine the role of the chemokine (C-X-C motif) ligand 9 (CXCL9) on nasopharyngeal carcinoma (NPC)." (PMID 24278236, 2013). "Based on these references CXCL9, CXCL10 and CXCL11 are likely to influence tumorigenesis from inflammation-related nasopharyngeal cancer." (PMID 32986378, 2020). "ZIC2 and OVOL1 may function in nasopharyngeal carcinoma through targeting significantly up-regulated genes (such as PTGS2, FN1, CXCL9 and CXCL10) in the Transcription factor-differentially expressed gene regulatory network (e.g., ZIC2→PTGS2 and OVOL1→CXCL10)." (PMID 27765529, 2017). "PTGS2, FN1, CXCL9, CXCL10, ZIC2 and OVOL1 might play roles in nasopharyngeal carcinoma." (PMID 27765529, 2017).
parasitemia (9 papers, 2010 to 2024). "We assessed the serum levels of six cytokines (i.e. IL-1α, IL-1β, IFNγ, CXCL10, CXCL9, TNFα) at the first peak of parasitemia of both 1/148 and IL3000 infections." (PMID 35787830, 2022). "Axl−/− macrophages had the highest expression of M1 responses, such as iNOS, NO, IL-12, and the M1-chemokine CXCL9, but reduced M2 (CD301) marker expression and better control of parasite infection." (PMID 36581764, 2022). "Of note, the perturbation of the liver damage parameters ALT, AST, total bilirubin, and also MDP values of IL-4, IL-6, IL-8, IL-12p70, CXCL9, CCL5, CCL2, CRP, fibrinogen and parasitemia levels showed an inverse correlation with the time living in the endemic area." (PMID 34727121, 2021). "Serum concentration of IL-1α, IL-1β, IFNγ, CXCL10, CXCL9, TNFα in non-infected mice and mice infected with either 1/148 or IL3000, at the first peak of parasitemia (Mean ± SEM; N=3–4)." (PMID 35787830, 2022).
renal cell carcinoma (9 papers, 2012 to 2024). "In renal cell carcinoma, endogenous CXCL9 was closely implicated in the antitumor effects that were produced by IL‐2 64 and IL‐12 (also producing CXCL10) 65 by inhibiting tumor angiogenesis and infiltration of CD8+ T lymphocytes, respectively." (PMID 27726306, 2016). "Compared with normal renal tissue, the mRNA expression of CXCR3/CXCL9/10/11 in renal cell carcinoma was significantly increased, and the upregulation of CXCR3 expression in renal cell carcinoma was related to the hypoxic state in TME." (PMID 39372416, 2024). "Sporadic instances of renal cell carcinomas in humans exhibit heightened expression levels of CXCL9, CXCL10, and CXCL11, hence facilitating the recruitment of T cells that possess CXCR3 and CCR5 receptors." (PMID 38730579, 2024). "However, future studies should aim to confirm the clinical and prognostic role of CXCL9–11/CXCR3 in renal cell carcinoma." (PMID 33202536, 2020). "Renal cell carcinoma, a typical immune-excluded tumor, is considered to lack the expression of some chemokines related to T cell recruitment, such as CXCL9, CXCL10, CXCL11, CXCL13, CX3CL1, CCL2, and CCL5, in its TME, but the specific mechanisms underlying this lack of chemokines remain unclear." (PMID 36397015, 2022). "In renal cell carcinoma (RCC), it was reported that high‐dose IL‐2 treatment in 20 patients elevated the plasma levels of CXCR3 ligands (CXCL9, CXCL10, and CXCL11), sequentially, forming an angiostatic environment." (PMID 27726306, 2016).
Stroke (9 papers, 2013 to 2025). Sudden impairment of blood flow to a part of the brain due to occlusion or rupture of an artery to the brain. "Although the higher levels of these cytokines might be explained by a higher number of CXCL9-producing monocytes and IL-3-producing T cells in the spleen, upregulation of chemotactic cytokines may provide a beneficial role after stroke by drawing inflammatory cells away from the brain." (PMID 33376583, 2020). "In the unstimulated saliva of stroke patients, we demonstrated significantly higher levels of chemotactic factors (CTACK/CCL27, IL-8/CXCL8, MIG/CXCL9, MIF) and growth factors (basic FGF, G-CSF, HGF, LIF, VEGF) compared to controls." (PMID 40221607, 2025). "Post‐stroke BHB therapy resulted in a substantial decrease in the expression of proinflammatory chemokines (CCL3, CXCL1, CXCL9, CXCL10), complement (C5/5a), cytokines (IFN‐γ), and myeloid cell activators (G‐CSF) in the ischemic hemisphere." (PMID 38666466, 2024). "At day 22, most of the measured cytokines were slightly (CINC-1, CINC-2α/β, CINC-3, GM-CSF and VEGF) or markedly (CD54, CD62L, CXCL7, CXCL9, CXCL10, CCL3, CCL5, CCL20) induced by stroke compared to Ctl." (PMID 33204331, 2020). "However, after adjusting for age, hypertension, atrial fibrillation, NIHSS admission score, right-sided lesion, and pre-stroke dependency in a multivariate analysis, only higher levels of CXCL10, CXCL9, and CXCL8 remained independent predictors of outcome." (PMID 38861234, 2025). "Further, young male mice had significantly higher expression of pro-inflammatory and chemotactic cytokines including Cxcl2/Mip2a (P = .0171), but not Cxcl9 and Il1b, after stroke, which was not seen in young females." (PMID 37910478, 2023). "Immunostaining demonstrated the expression of CXCL10 protein, but not CXCL9 or CXCL11, along CD31+ vessels in the ischemic brain 1 day after stroke." (PMID 35912857, 2022).
Alzheimer disease (8 papers, 2014 to 2026). A progressive, neurodegenerative disease characterized by loss of function and death of nerve cells in several areas of the brain leading to loss of cognitive function such as memory and language. "Essentially, many comorbidities of rosacea, such as Alzheimer’s disease and inflammatory bowel disease have shown an association with chemokines CXCL9 and CXCL10 in the circulating serum." (PMID 36091020, 2022). "We observed some evidence for a detrimental effect of greater levels of CTACK (CCL27), MIP-1b (CCL4), Eotaxin, GROa (CXCL1), MIG (CXCL9), IL-8 and IL-2 on the risk of Alzheimer’s disease." (PMID 35580794, 2022). "It has also been shown that CXCL9 and CXCL10 can induce ERK1/2 activation in mouse cortical neurons, which may promote their survival, but has also been associated with neuronal cell death in models of epilepsy, ischemia, and Alzheimer’s disease." (PMID 24924222, 2014). "Regarding Alzheimer’s disease, a cross-sectional study reported substantially higher levels of circulating MIG (CXCL9) in patients with Alzheimer’s disease compared to non-cognitively impaired and mildly-cognitively impaired participants." (PMID 35580794, 2022). "CTACK (CCL4), MIG (CXCL9), GROa (CXCL1), MIP-1b (CCL4), Eotaxin (CCL11) and IL-8 belong to the chemokine family and evidence suggest that they could potentially play a role in Alzheimer’s disease." (PMID 35580794, 2022).
Hepatitis (8 papers, 2013 to 2023). Inflammation of the liver. "In Con A-induced hepatitis, we found CXCL9 in the inflamed liver to be closely associated with LSEC, which represent the first contact site for T-cell immigration into the liver." (PMID 26052942, 2015). "Investigation of hepatitis parameters showed slight CXCL9-dependant differences in leukocyte infiltration of murine MAS hepatitis." (PMID 37516815, 2023). "Plus, additional chemokines, CXCL-9 and CXCL-10, were higher in men and have been associated with liver inflammation." (PMID 35493503, 2022). "In human study, elevated CXCL9 and IP-10 involve in liver inflammation during hepatitis flares in CHB." (PMID 24124595, 2013). "Results showed that CXCL9 genetic deficiency did not improve disease parameters or hepatitis in both models." (PMID 37516815, 2023). "Apart from our studies and findings, a prior comprehensive review indicated enhanced expression of Th1 phenotypic cytokines (IL-2 and IFN-γ), and high serum levels of IFN-γ inducible chemokines CXCL-9 and CXCL-10 during the process of hepatitis flare." (PMID 35163330, 2022). "High serum IFN-γ inducible chemokines CXCL-9 and CXCL-10 levels were also found to correlate with the development of hepatitis flares." (PMID 35163330, 2022). "CXCL9 and CXCL10 mRNA expression decreased over time whereas CXCL12 recovered to its initial levels within 24 h after hepatitis induction." (PMID 26052942, 2015). "We quantified the fraction of hepatic CD4+ T cells expressing CXCR3, the receptor for CXCL9 and CXCL10 that were strongly up-regulated at an early stage of Con A-induced hepatitis." (PMID 26052942, 2015). "The mRNA expression of inflammatory CXCL9 and CXCL10 was significantly increased 3 h after induction of hepatitis, a time point well before liver damage became detectable by plasma ALT levels." (PMID 26052942, 2015). "CXCL9 (monokine induced by IFN-γ [MIG]) and IP-10 (IFN-γ-inducible protein 10, also called CXCL10) have been reported to play important roles during hepatitis flares in CHB." (PMID 24124595, 2013).
inflammatory bowel disease (8 papers, 2013 to 2025). A spectrum of small and large bowel inflammatory diseases of unknown etiology. "CXCL9 is highly expressed in response to infection of some intestinal pathogens (e.g., Citrobacter rodentium), though it is unknown whether expression of CXCL9 can also be induced by F. nucleatum, a proinflammatory pathogenic bacteria which is related to inflammatory bowel disease." (PMID 37237391, 2023). "While chemokines are known to play a key role in the intestinal mucosal homeostasis and pathogenesis of inflammatory bowel diseases, chemokines such as CXCL9/MIG and CXCL10/IP-10 are overexpressed in colon cancer." (PMID 26951793, 2016). "CXCL9, CXCL10 and CXCL11 can activate T cells by binding to C-X-C motif chemokine receptor (CXCR) 3 and have been implicated in a variety of autoimmune diseases, including thyroiditis, systemic sclerosis, and inflammatory bowel disease (IBD)." (PMID 35464480, 2022). "Moreover, decreased levels of miRNA-200a-3p, which is highly abundant in mEVs, were associated with bovine milk EV depletion in the mouse diet and exacerbated the inflammatory bowel disease (IBD) symptoms through chemokine (C-X-C motif) ligand 9 (CXCL9) production." (PMID 36496752, 2022). "In addition, in inflammatory bowel disease (IBD), perforin produced by colon CD8+ T cells promotes the expression of C-X-C motif chemokine ligand 9 (CXCL9), inducing ERS in hippocampal neurons and exacerbating depression associated with IBD." (PMID 40936908, 2025). "CXCR3 and its ligands CXCL9, CXCL10, and CXCL11 are differentially elevated in many instances, such as with periodontal, autoimmune liver diseases, multiple sclerosis, bronchiolitis, skin or mucosal inflammation, cyclophosphamide (CYP)-induced cystitis, and inflammatory bowel disease (IBD)." (PMID 24278169, 2013).
Kawasaki disease (8 papers, 2015 to 2025). A rare inflammatory disease characterized by an acute febrile, systemic, self-limiting, medium-vessel vasculitis primarily affecting children. "Rodriguez-Smith’s data reveal that MIS-C can be distinguished from Kawasaki disease predominantly by higher IFN-γ-induced chemokine CXCL9 levels: the CXCL9 concentration has also been documented as related to disease severity." (PMID 37240926, 2023). "In external dataset B dataset which had a Kawasaki disease cohort, CXCL9 was elevated in MIS-C compared with the Kawasaki cohort, consistent with the findings of increased abundance of CXCL9 in MIS-C cohorts compared with disease controls in our study and in the other datasets." (PMID 40826070, 2025). "Plasma concentrations of ARG1, CCL20, CD163, CORIN, CXCL9, PCSK9 and ADAMTS2 were quantified in MIS-C (n = 22), Kawasaki disease (n = 23), definite bacterial (n = 28) and viral (n = 27) disease and healthy controls (n = 8)." (PMID 38359342, 2024). "CXCL9 has been increasingly reported as a key biomarker in MIS-C due to its role in macrophage activation and Th1-driven cytokine responses, with several studies highlighting its discriminative value compared to other febrile inflammatory syndromes such as Kawasaki disease." (PMID 40430232, 2025).
lung adenocarcinoma (8 papers, 2020 to 2025). A carcinoma that arises from the lung and is characterized by the presence of malignant glandular epithelial cells. "After Bonferroni correction, CXCL9 remained significantly related to the risk of early-stage lung adenocarcinoma recurrence." (PMID 32714866, 2020). "Lung adenocarcinoma patients with high CXCL9 levels had a 71% reduced risk of recurrence relative to patients with low CXCL9 levels (HR = 0.29, 95% CI: 0.13–0.64, p = 0.0021)." (PMID 32714866, 2020). "The association of CXCL9 with DFS in lung adenocarcinoma patients was stratified by age, sex, and smoking status." (PMID 32714866, 2020). "In our previous study, a high CXCL9 level was found to be related to a reduced risk of lung adenocarcinoma." (PMID 32714866, 2020). "Significant association of CXCL9 in overall survival (OS) of lung adenocarcinoma." (PMID 32714866, 2020). "Lung adenocarcinoma patients with high CXCL9 levels had an 80% reduced risk of death relative to patients with low CXCL9 levels (HR = 0.20, 95% CI: 0.05–0.78, p = 0.021), and those in the TCGA validation cohort were at a 29% reduced risk of death (HR = 0.71, 95% CI: 0.45–0.99, p = 0.044)." (PMID 32714866, 2020). "We identify significantly increased expression of PDL2 and CXCL9 in lung adenocarcinoma with age in TCGA." (PMID 34433020, 2021). "The application of CXCL9 as a predictive and prognostic biomarker of early-stage lung adenocarcinoma patients will be investigated in the future with large, well-designed, multicenter cohort studies, along with in vitro and in vivo functional experiments." (PMID 32714866, 2020). "K–M analysis showed that lung adenocarcinoma patients with high CXCL9 levels had a significantly longer median DFS time than those with low CXCL9 levels (log-rank test p = 0.014)." (PMID 32714866, 2020). "The key finding of the present study was that CXCL9, a chemokine, was associated with both the DFS and OS of early-stage lung adenocarcinoma patients." (PMID 32714866, 2020). "Stratified analyses of CXCL9 on disease-free survival in early stage lung adenocarcinoma." (PMID 32714866, 2020). "NE can affect the secretion of CXCL9 and ADO in tumour cells, thereby inhibiting chemotaxis and the function of CD8+ T cells and inducing anti-PD-1 mAb resistance in lung adenocarcinoma (LUAD)." (PMID 36646807, 2023). "In the present study, high CXCL9 levels were found to be related to prolonged DFS and OS in early-stage lung adenocarcinoma patients." (PMID 32714866, 2020). "Our findings demonstrate for the first time that the CXCL9 level is as a protective factor for both the DFS and OS of early-stage lung adenocarcinoma patients." (PMID 32714866, 2020). "Analysis of NSCLC data from The Cancer Genome Atlas (TCGA) identified a strong correlation (Spearman correlation coefficient >0.55) among the expression of CXCL9, CXCL10, and their cognate receptor (CXCR3) in both lung adenocarcinoma (LUAD) and lung squamous carcinoma (LUSC)." (PMID 38518770, 2024). "Elevated CXCL9 levels were found to predict a good prognosis in never smokers, females, and both young and old lung adenocarcinoma patients." (PMID 32714866, 2020). "The K-M analysis showed that increased CXCL9 levels were still significantly corelated with longer DFS in never smokers and young lung adenocarcinoma patients." (PMID 32714866, 2020).
pulmonary TB (8 papers, 2009 to 2025). "Previous literature showed that the expression of CXCL8 and CXCL9 in the serum of patients with active pulmonary tuberculosis is elevated and returns to normal levels after 4–6 months of treatment." (PMID 36992931, 2023). "IL10 combined with CXCL-9 distinguished pulmonary tuberculosis patients from extrapulmonary cases with a sensitivity, specificity, and accuracy of 85.7%, 73.9%, and 81.0%, respectively." (PMID 32962082, 2020). "CXCL9 has been shown to be induced by ESAT6 in patients with pulmonary TB." (PMID 19340290, 2009).
serous ovarian cancer (8 papers, 2020 to 2024). "Tumors with high CXCL9 expression had significantly prolonged OS, implying the feasibility of CXCL9 expression as a novel prognostic marker for high-grade serous ovarian cancer (HGSC)." (PMID 36389711, 2022). "CXCL9 can predict survival and is regulated by cyclooxygenase inhibition in advanced serous ovarian cancer." (PMID 34054929, 2021). "Notably, in advanced high-grade serous ovarian cancer, patients presenting with an increased expression of CXCL9/10 demonstrated improved clinical outcomes." (PMID 38275602, 2024). "Critically for the clinical context, recent studies have indicated better prognosis among high-grade serous ovarian cancers with high CD8+ T cell infiltrates and CXCL9 levels, supporting the potential clinical significance of our approach." (PMID 33028251, 2020).
triple-negative breast carcinoma (8 papers, 2020 to 2026). An invasive breast carcinoma which is negative for expression of estrogen receptor (ER), progesterone receptor (PR), and human epidermal growth factor receptor 2 (HER2). "For the first time, we found that nsPEF’s growth inhibition of residual triple negative breast cancer cells in mice was dependent on CXCL9 axis." (PMID 37046739, 2023). "However, the relationship between CXCL9 expression and prognosis in triple-negative breast cancer (TNBC) is unclear." (PMID 38957805, 2024). "Anti-CXCL9 was used alone or combined with nsPEF to treat triple-negative breast cancer in mice." (PMID 37046739, 2023). "Moreover, the expression level of CXCL9 significantly increased in triple negative breast cancer patients compared with the HER2-enriched or ER-positive breast cancer patients." (PMID 35052427, 2021). "Recently, it has been shown that LSD1 inhibition in triple negative breast cancer cell lines induces expression of CD8+ T cell-attracting chemokines, including CCL5, CXCL9, and CXCL10." (PMID 32649682, 2020). "For example, CXCL9—a Th1 chemokine that recruits CD8+ T cells—is recognized as a biomarker for “immunologically hot” tumors and predicts positive response to immune checkpoint inhibitors (e.g., pembrolizumab) in triple-negative breast cancer." (PMID 41462979, 2025).